LEP (leptin)
Diseases named in the same sentence as LEP in open-access papers (continued):
Sharing a sentence is not in itself a finding about the gene and the disease.
breast cancer (continued). "Among ER+ breast cancer patients, BMI, leptin and IL-6 significantly correlated with T status and presence of distant metastases (M+)." (PMID 25338520, 2014). "In our study, we reported a significant reduction in the levels of the adipocytokine leptin, that has been reported to stimulate mammary tumor growth." (PMID 25147760, 2014). "Leptin increased the expression and activation of several members of the Notch family of proteins in breast cancer cells and derived tumors." (PMID 24716804, 2014). "Furthermore, assuming the reported associations between circulating leptin concentrations and breast cancer risk and adverse events in breast cancer survivors are accurate, interventions targeting leptin may be promising for breast cancer prevention and control efforts in the future." (PMID 24790820, 2014). "A significant positive relationship was found between leptin and BMI in ER+ and ER− breast cancer patients." (PMID 25338520, 2014). "Our results are consistent with previous studies showing similar leptin induction of cyclin D1 expression in human breast cancer, the colon cancer cell line HT-29, and human hepatocarcinoma cells." (PMID 22968658, 2013). "More recently leptin was shown to activate Notch signaling pathway in breast cancer and endothelial cells under normoxic conditions." (PMID 24202338, 2013). "Overall, leptin induction of proliferation/migration and upregulation of VEGF/VEGFR2 in breast cancer cells were related to an intact leptin-Notch-IL-1 signaling axis." (PMID 24202338, 2013). "Leptin, the main adipokine secreted by adipose tissue, is also abnormally expressed together with its receptor (OB-R) by breast cancer cells." (PMID 24202338, 2013). "In whole tissue breast cancer tissue arrays (n = 75; Pantomics, Inc., Richmond, CA, USA), leptin and OB-R stained cells were detected in 46%−70% of samples." (PMID 24202338, 2013). "ASCs isolated from the abdomen of obese subjects demonstrated increased expression of leptin, through estrogen stimulation, which increased breast cancer cell proliferation." (PMID 24176089, 2013). "We demonstrated that leptin and adiponectin exert opposing activities on the angiogenesis process, and that leptin is able to interact with various drugs clinically used in the management breast cancer." (PMID 23554900, 2013). "Conversely, leptin transactivated ER and increased the expression of aromatase in breast cancer cells." (PMID 24202338, 2013). "While a number of studies reported leptin level in breast cancer and controls using a frequency table, others reported results as medians and interquartile ranges instead of means and SDs." (PMID 23826274, 2013). "After exposure to estrogen the ASCs increased in leptin expression and breast cancer cell proliferation and tumor growth, suggesting that a threshold of expression must be achieved before leptin can effectively activate breast cancer cell proliferation." (PMID 24176089, 2013). "VEGF concentrations were measured in MCF7 and MDA-MB-231 mammary tumor cells after 72-h stimulation with leptin (10 to 1 000 ng/ml)." (PMID 23554900, 2013). "Leptin has been shown to play a vital role in the progression of breast cancer through the activation of several signaling cascades." (PMID 24176089, 2013). "The analysis of leptin expression in primary breast cancer samples demonstrated significant differences in normal breast tissue compared to invasive ductal carcinoma." (PMID 24176089, 2013). "Women diagnosed with estrogen receptor/progesterone receptor positive (ER+/PR+) breast cancers that also expressed high levels of leptin had poorer prognosis than women with low leptin expression." (PMID 24176089, 2013). "Inhibitory studies were conducted by delivering estrogen antagonist ICI182,780, leptin neutralizing antibody, or aromatase inhibitor letrozole and assessing breast cancer cell proliferation." (PMID 24176089, 2013).
breast cancer (continued). "In vitro assays studying the effects of leptin and adiponectin on cell proliferation have found a stimulatory role of leptin and an inhibitory role of adiponectin in mammary tumor growth." (PMID 23554900, 2013). "Comprehensive mechanisms for leptin upregulation of VEGF/VEGFR2 transcriptional expression in breast cancer cells have been reported." (PMID 24202338, 2013). "In line with previous reports from human monocytes, leptin induced IL-1β and IL-1Ra expression in breast cancer cells, which was related to the phosphorylation of mTOR/4E-BP1." (PMID 24202338, 2013). "It has in fact been shown in MCF7, MDA-231 and MDA-468 breast cancer cells that treatment with leptin can phosphorylate IGF1R and activate downstream signaling while treatment with IGF1 phosphorylates leptin receptor and activates downstream signaling." (PMID 24260287, 2013). "PEG-LPrA2 treatment decreased levels of human and mouse VEGF and leptin in MCF-7 ER+ breast cancer xenografts." (PMID 24202338, 2013). "For groups D and F, the leptin level was higher in breast cancer patients than that of breast benign controls." (PMID 23826274, 2013). "VEGF promoter deletion and siRNA analyses showed that leptin signaling regulates VEGF in breast cancer mainly through HIF-1α and NFκB in normoxic conditions." (PMID 24202338, 2013). "Several studies suggest that leptin also exhibits estrogen-producing activity by enhancing aromatase expression and enhances the sensitivity of breast cancer cells to estrogen through the up-regulation of estrogen receptor alpha." (PMID 24176089, 2013). "The strength of the present study is that it is the first systematic review and meta-analysis, to our knowledge, to evaluate the relationship between serum leptin level and breast cancer." (PMID 23826274, 2013). "Insulin also induces leptin expression in breast cancer cells by increasing HIF-1α and SP1 binding to the leptin promoter." (PMID 24202338, 2013). "The results for group B and C were similar to group A. The leptin level of breast cancer patients for group B and C was higher than that of healthy controls, regardless of menopausal status." (PMID 23826274, 2013). "Accumulated evidence suggested that leptin signaling gave an additional advantage to breast cancer progression by upregulating VEGF/VEGFR2 before hypoxia occurred." (PMID 24202338, 2013). "Specific adipokines that stimulate the proliferation of human estrogen receptor (ER) positive breast cancer cells are leptin, collagen VI, and members of the insulin-like growth factor (IGF) family of proteins." (PMID 24171117, 2013). "Leptin enhances breast cancer cell proliferation by inhibiting pro-apoptosis signalling pathways and by favouring in vitro sensitivity to oestrogens." (PMID 23826274, 2013). "The link between high leptin expression and prognosis for breast cancer patients was determined to be significant in ER+/PR+ breast cancer." (PMID 24176089, 2013). "In breast cancer cells leptin induced the transcriptional and translational expression of IL-1 family of proteins." (PMID 24202338, 2013). "In order to assess expression of leptin in human breast cancer samples, leptin expression was analyzed using the TCGA cDNA microarray data set of breast cancers deposited in Oncomine." (PMID 24176089, 2013). "Estrogen and progesterone unresponsive breast cancers are mostly dependent on growth factors (i.e., insulin, insulin-like growth factor-I) and adipokines (i.e., leptin)." (PMID 24202338, 2013). "In breast cancer, IL-1 increased leptin expression in stromal cells recruited into the tumor microenvironment." (PMID 24202338, 2013).
breast cancer (continued). "More detailed analysis of primary breast cancer samples is needed to assess the cell type expressing the leptin." (PMID 24176089, 2013). "Leptin can be activated in response to hypoxia in breast cancer cells where the process is mediated through hypoxia-inducible factor-1." (PMID 23815123, 2013). "Our results are consistent with previous studies showing a similar decrease in p21WAF1/CIP1 expression under the influence of leptin in human breast cancer cells and Ishikawa human endometrial cancer cells." (PMID 22968658, 2013). "In ER positive breast cancer cells, leptin through its cognate membrane spanning cytokine leptin receptor activates the JAK/STAT pathway." (PMID 24171117, 2013). "In this study we demonstrate that hyperglycemia promotes breast cancer by altering leptin/IGF1R and AKT/mTOR signaling." (PMID 24260287, 2013). "Overall the results of this study suggest that the circulating leptin level varies among these different population groups from low to high: healthy people<breast benign diseases patients<breast cancer patients <lymph node metastasis positive patients." (PMID 23826274, 2013). "We have demonstrated that leptin and adiponectin, the two main adipokines studied, exert proliferative and antiproliferative activities respectively on breast cancer cells in vitro." (PMID 23750285, 2013). "Overall, the leptin level of the four population can be ranked as follows: healthy controls<breast benign diseases patients<breast cancer patients<lymph node metastasis positive breast cancer patients." (PMID 23826274, 2013). "We previously reported that the adipokines leptin and adiponectin were expressed in breast cancer tissue and had proliferative (leptin) and anti-proliferative (adiponectin) effects on breast cancer cell lines." (PMID 23554900, 2013). "There is also evidence demonstrating that leptin enhanced the expression of OBRs, for example in ZR-75-1 breast cancer cells." (PMID 23425972, 2013). "Remarkably, in breast cancer leptin upregulated Notch1-4/JAG1/Dll-4, Notch target genes: Hey2 and survivin, together with IL-1 and VEGF/VEGFR2." (PMID 24202338, 2013). "A number of studies indicate that LEPR are overexpressed in many tumor tissues and that there are leptin-responsive tumors including mammary carcinomas, pancreatic, esophageal, gastric, and colon tumors." (PMID 23819063, 2013). "Leptin has been shown to positively influence breast cancer cell proliferation, invasion, and metastasis in vitro and in vivo." (PMID 23342276, 2012). "It appears to function in opposition of leptin, blocking its tumorigenic effects, and an increased ratio of leptin to adiponectin leads to tumor proliferation in breast cancer cells." (PMID 23050155, 2012). "Leptin exerts its metabolic effects as well as biological activities, such as cell proliferation, apoptosis and survival on breast cancer cells." (PMID 22929622, 2012). "Since leptin promotes breast tumor growth and adiponectin has anticancer properties, it has been suggested that the adiponectin:leptin ratio is a critical factor in mammary cancer tumorigenesis." (PMID 23272114, 2012). "Previous reports indicated that leptin increases VEGF synthesis and VEGFR2 expression by breast cancer cells and suggested that leptin and VEGF can cooperate to promote angiogenesis in vivo, but the molecular basis of this interaction is not characterised." (PMID 21533119, 2011). "We have previously shown that leptin induces growth and angiogenesis in mouse syngeneic mammary tumors, human breast cancer xenografts and, in a mouse model for endometriosis-like lesions." (PMID 21731759, 2011). "Our results show for the first time that leptin is a regulator of Notch expression and activation in breast cancer." (PMID 21731759, 2011).
breast cancer (continued). "Present study further supports the idea that leptin has an important role in breast cancer by increasing the expression of pro-angiogenic and pro-inflammatory factors." (PMID 21139583, 2011). "Leptin promotes breast cancer cell growth, whereas adiponectin reduces cell proliferation and enhances apoptosis." (PMID 22030015, 2011). "In conclusions, Notch-IL-1-Leptin crosstalk outcome (NILCO) is essential for leptin-induced proliferation/migration as well as the upregulation of VEGF/VEGFR-2 expression in breast cancer cells." (PMID 21731759, 2011). "We have previously reported that leptin induces the growth of breast cancer and the expression of VEGF/VEGFR-2 and IL-1 system." (PMID 21731759, 2011). "Accumulating evidence suggest that leptin is an important player in breast cancer growth and tumour angiogenesis." (PMID 21139583, 2011). "We show for the first time that a novel unveiled crosstalk between Notch, IL-1 and leptin (NILCO) occurs in breast cancer." (PMID 21731759, 2011). "Leptin-induction of cell proliferation/migration along with VEGF/VEGFR-2 was highly dependent of a novel unveiled crosstalk between Notch, IL-1 and leptin (NILCO) in breast cancer cells." (PMID 21731759, 2011). "Leukaemia inhibitory factor, VEGF, interleukin-1 (IL-1) and leptin are known angiogenic factors expressed by mammary cancer cells." (PMID 21139583, 2011). "We show for the first time that leptin induces several signalling pathways to upregulate the translational and transcriptional expression of IL-1 system in breast cancer cells." (PMID 21139583, 2011). "Breast carcinoma cells express higher levels of leptin and its receptor, Ob-R, than normal mammary cells, and a significant correlation between leptin/Ob-R levels with metastasis and lower survival of breast cancer patients has been found." (PMID 21139583, 2011). "Notch, IL-1 and leptin are notorious pro-angiogenic factors whose over-expression characterized growth of breast cancer, metastasis and poor prognosis." (PMID 21731759, 2011). "IL-1/IL-1R tI signals were previously found to mediate leptin upregulation of VEGF/VEGFR-2 in breast cancer." (PMID 21731759, 2011). "We also have evidence showing that leptin, which plays a role in breast cancer development in obesity, induces human breast cancer epithelial cell sensitivity to Z." (PMID 21673905, 2011). "Leptin-induced proliferation and migration effects as well as increased levels of pro-angiogenic factors in breast cancer cells were related to an intact Notch signaling axis." (PMID 21731759, 2011). "Nevertheless, published studies on the relationships between leptin and IL-1 in breast cancer are scarce." (PMID 21139583, 2011). "Leptin and leptin receptor are involved in the development of normal mammary glands and in the progression of breast cancer." (PMID 21834963, 2011). "We have recently described a comprehensive mechanism for leptin upregulation of VEGF in breast cancer." (PMID 21731759, 2011). "Recently, we demonstrated that in breast cancer cells, leptin and ObR expression can be activated in response to hypoxia or hyperinsulinemia." (PMID 20569445, 2010). "Here we analyzed the relationships between hypoxia-related proteins (HIF-1α, Glut-1, leptin, ObR) and other cancer biomarkers in primary breast cancer and lymph node metastases." (PMID 20569445, 2010). "In vitro, leptin has been shown to increase cell motility and decrease cell apoptosis in breast cancer cell lines." (PMID 19672469, 2009). "Regardless of the impact of circulating leptin, more research is needed to elucidate molecular mechanisms and local leptin levels that are critical for the development of breast cancers." (PMID 19223908, 2009). "In conclusion, the converging lines of evidence from this study and earlier in vitro studies provide the background biological context for considering a role for leptin in the pathogenesis of breast cancer." (PMID 19223908, 2009).
breast cancer (continued). "As an adipocyte-derived cytokine, leptin acts pro-inflammatory through induction of cytokines by T cells, but it has also been identified as a growth factor for breast cancer." (PMID 19348684, 2009). "Leptin exerts its growth effect on breast cancer cell lines through activation of multiple signaling cascades, including the JAK/STAT, ERK1/2, PKC- alpha and PPAR signaling pathways." (PMID 21566743, 2008). "Next, we studied if leptin/ObR can coexist with HER2 in breast cancer tissues, and if presence of these two systems correlates with specific clinicopathological features." (PMID 18945363, 2008). "An inverse relationship of circulating adiponectin levels and breast cancer risk in postmenopausal women was observed independently of possible effects of IGF-1, leptin, and BMI." (PMID 21566743, 2008). "Circulating leptin and leptin mRNA expression levels were both elevated in breast cancer patients and increase in leptin mRNA expression levels." (PMID 21566743, 2008). "Additional experiments will confirm and define the roles of adipokines such as Acrp30 and leptin and determine how the balance of the two impact breast cancer cell growth and death." (PMID 18182989, 2008). "We noted that the leptin/ObR system is coexpressed with HER2 in a large fraction of breast cancers, which supports the possibility of intratumoral ObR/HER2 interactions." (PMID 18945363, 2008). "Expression of leptin and its receptors were found in normal mammary tissue, as well as breast cancer tissue." (PMID 21566743, 2008). "In summary, our results suggest the existence of crosstalk between HER2 and the leptin system in breast cancer." (PMID 18945363, 2008). "Despite these premises, very few studies have considered the role of serum leptin levels and polymorphisms in leptin and LEPR genes in breast cancer risk." (PMID 19017403, 2008). "New evidence obtained in cellular and animal breast cancer models suggests that leptin, the major hormone produced by the fat tissue, can be mechanistically involved in these neoplastic processes." (PMID 18945363, 2008). "We feel that factors in the serum of the mice, specifically adipokines have the ability to function as both growth stimulators such as has been shown for leptin or as growth inhibitors such as seems to be the case with Acrp30 for breast cancer." (PMID 18182989, 2008). "The biological effect of leptin on breast cancer came from the findings of leptin-induced proliferation of breast cancer cells." (PMID 21566743, 2008). "Especially, circulating leptin concentrations are correlated with the incidence of breast carcinoma." (PMID 21566743, 2008). "Leptin has also been shown to counteract the anti-tumorigenic activities of anti-estrogens in breast cancer cells." (PMID 17229323, 2007). "For example, increased cell proliferation was observed when human breast cancer cells were incubated with leptin in in vitro studies." (PMID 18162139, 2007). "Leptin stimulates the growth of breast cancer cell lines in vitro and can induce the expression of proteolytic enzymes which are essential for breast cancer cell invasion." (PMID 17229323, 2007). "For model 1 (adjusted for age, race, family history of breast cancer, parity, and menarche < 12 years), we found statistically significant increases in the concentrations of serum leptin for all five measures of adiposity." (PMID 17229323, 2007). "Genotype frequencies of LEP and LEPR polymorphisms in relation to pathological indices of breast cancer severity." (PMID 16504019, 2006). "In breast cancer tissue, it was shown that leptin and leptin receptor are both expressed and that they act to favour cancer proliferation and metastasis." (PMID 16504019, 2006). "The role of the leptin and its receptor as genetic markers for breast cancer can be completed with other SNPs and a haplotype analysis." (PMID 16504019, 2006).